KRT1 (keratin 1)
Diseases named in the same sentence as KRT1 in open-access papers (continued):
Sharing a sentence is not in itself a finding about the gene and the disease.
papilloma (6 papers, 2010 to 2023). A benign epithelial neoplasm that projects above the surrounding epithelial surface and consists of villous or arborescent outgrowths of fibrovascular stroma. "Increased susceptibility to papilloma was also observed in the transgenic mice that express IGF1 under keratin-1 or keratin-5 gene promoter." (PMID 30981207, 2019). "Moreover, we confirmed the contribution of HF stem cells to the development of papillomas as well as ulcer-associated dysplasia by placing Krt1-15CrePr;R26R mice in protocols for BMT and chemical carcinogenesis." (PMID 30546048, 2018). "Of note, iASPP-KO papillomas showed increased numbers of cells strongly positive for differentiation markers keratin 1 (CK1) and involucrin." (PMID 36261000, 2022). "Immunohistochemical analysis of the mildly hyperplastic “normal” skin of the nude mouse, compared to trichoblastomas and papillomas, revealed similar patterns of protein expression for KRT1 and 10 which are normally expressed in the suprabasilar epidermis." (PMID 25474466, 2014). "In the papillomas, KRT1 was suprabasilar in hyperplastic epidermis adjacent to the papilloma but was expressed in all layers in the papillomatous areas." (PMID 25474466, 2014). "Transgenic mice that overexpress TGFα in the skin via either a K14 or keratin 1 (K1) promoter develop papillomas upon wounding or with TPA treatment without carcinogen initiation, demonstrating that high expression levels of TGFα can act as an initiating event, as well as enhance tumor promotion." (PMID 21297902, 2010).
bladder cancer (5 papers, 2003 to 2024). "Using a combination of the two drugs, several proteins associated with the basal subtype of bladder cancers were consistently decreased within both cell lines such as KRT1, KRT14, KRT16, P63, and TFAP2A." (PMID 32822399, 2020). "Hsp74 was associated with keratin 1 as determined by coimmunoprecipitation from bladder cancer cell line BLZ211." (PMID 25050384, 2014). "However, a combined treatment of TG and PD resulted in a consistent decrease of several proteins associated with the basal subtype of bladder cancers (KRT1, KRT14, KRT16, P63, and TFAP2A)." (PMID 32822399, 2020). "In addition, these data represent the first report, to our knowledge, of a functional link between Hsp74 and keratin 1 in bladder cancer cells." (PMID 25050384, 2014). "Our laboratory demonstrated that arsenite-transformed malignant UROtsa cells exhibit characteristics of the basal muscle-invasive phenotype of bladder cancer, including high expression of basal markers such as EGFR, KRT1, KRT5, and KRT6." (PMID 38539513, 2024).
cervical cancer (4 papers, 2022 to 2025). A primary or metastatic malignant neoplasm involving the cervix. "In cervical cancer, KRT1 (type II; “acidic” keratin) and KRT10 (type I; “basic” keratin) are upregulated in cervical cancer." (PMID 36765810, 2023). "The increased expression of KRT1 in cervical cancer cell was not statistically significant, and interestingly, which was contrary to the expression trend of KRT1 in GEO datasets." (PMID 39060960, 2024). "The expression of KRT1 was increased in cervical cancer cell, but there was no statistical significance compared with normal cell, and, interestingly, this was contrary to the trend of KRT1 expression in GEO datasets." (PMID 39060960, 2024). "The antibody CAB002153 did not detect KRT1 in normal cervix tissues, and it was stained with low intensity in cervical cancer tissues, and the proportion of stained cells was < 25%." (PMID 39060960, 2024). "Thus, it is suggested that KRT1 and KRT10 are involved in the proliferation of cervical keratinocytes in cervical cancer." (PMID 36765810, 2023). "However, interestingly, the TCGA database and GEPIA online website analysis showed that TOP2A, AURKA, CCNA2 and IVL were overexpressed and IGFBP5 was low expression in cervical cancer, and there was no statistical difference in the expression of KRT1 in cervical cancer tissue and normal tissue." (PMID 39060960, 2024). "The TOP2A, AURKA and CCNA2 in cervical cancer were significantly increased, while IVL, KRT1, and IGFBP5 were significantly decreased, compared with normal tissues, which was consistent with the screening results." (PMID 39060960, 2024).
cholesteatoma (4 papers, 2012 to 2018). A pathologic process characterized by the proliferation of keratinizing squamous epithelium resulting in the accumulation of keratin and cells in the middle ear and/or mastoid. "Culture supernatants collected from the cholesteatoma-associated fibroblasts were able to increase the proliferation and differentiation of human keratinocytes assessed by the expression of Ki67 and keratin-1 markers." (PMID 22481617, 2012). "In our cholesteatoma samples KRT1 and KRT10 showed identical expression patterns as it was expected, since they protein products are known to form heteroduplex in cells." (PMID 30021014, 2018). "KRT1, 4, 5, 6, 7, 8, 10, 13, 14, 15, 16, 17, 18 and 19 have previously been detected in human cholesteatoma tissue." (PMID 25093596, 2014). "The differences in the expression pattern of the KRT1 and KRT10 genes observed in our study support the hypothesis that distinctly altered cellular differentiation processes are associated with cholesteatoma formation in pediatric and adult cases." (PMID 30021014, 2018). "Based on our results it can be concluded that the expression pattern of KRT1, KRT10 and KRT19 genes seen in our pediatric cholesteatoma samples suggests elevated immature keratinocyte differentiation and elevated proliferation potential, especially in recurrent samples." (PMID 30021014, 2018).
ovarian carcinoma (4 papers, 2011 to 2025). A malignant neoplasm originating from the surface ovarian epithelium. "Interestingly, in a cisplatin-resistant human ovarian cancer cell line, KRT1 showed significant differential expression in proteomic analysis, and another study revealed that KRT1 may be associated with chemotherapy sensitivity in nasopharyngeal cancer." (PMID 41002590, 2025). "Some studies have shown that KRT1 is correlated with chemotherapy resistance and sensitivity in human ovarian cancer cell lines and nasopharyngeal cancer." (PMID 41002590, 2025).
squamous carcinomas (4 papers, 2019 to 2023). "Additionally, a 3D culture system using human squamous carcinoma cells (TR146) was used to evaluate and correlate the changes in the expression of type XVIII collagen gene, COL18A1, and epithelial keratinization-related markers, e.g., keratin 1 (KRT1) and 10 (KRT10)." (PMID 31554264, 2019).
colon carcinoma (3 papers, 2014 to 2020). "In addition, KRT1 was significantly overexpressed in colon cancer, especially in its later phase." (PMID 33323544, 2020).
COVID-19 (3 papers, 2024 to 2025). A disease caused by infection with severe acute respiratory syndrome coronavirus 2. "Limited work has suggested a role for KRT1 in COVID-19 progression in humans, and keratins are common contaminants in mass spectrometry." (PMID 40815262, 2025).
epidermolytic palmoplantar keratoderma (3 papers, 2023 to 2026). "Epidermolytic palmoplantar keratoderma (EPPK) is typically caused by variations in KRT9 or KRT1 genes." (PMID 41601798, 2026).
Harlequin ichthyosis (3 papers, 2019 to 2022). Harlequin ichthyosis (HI) is the most severe variant of autosomal recessive congenital ichthyosis (ARCI; see this term). "Interestingly, some of these genes, i.e. KRT1, KRT9, KRT16, DSG1, DSC2 and JUP, are mutated in hereditary PPKs, while the ABCA12 gene is defective in harlequin ichthyosis characterized by the loss of the skin lipid barrier." (PMID 35854363, 2022).
keloid (3 papers, 2022 to 2023). An irregularly shaped, elevated mark on the skin caused by deposits of excessive amounts of collagen during wound healing. "Most keratins were downregulated in keloids, including KRT10, KRT14, KRT15, KRT19, KRT1, KRT77, and KRT5." (PMID 35435317, 2022).
keratoconus (3 papers, 2021 to 2026). A degenerative, structural disorder of the eye, characterized by a cone-shaped protrusion of the cornea. "Among all the listed keratins only KRT1, KRT4, KRT76, and KRT78 are upregulated in keratoconus all the other keratins are not differentially expressed." (PMID 37279397, 2023).
viral infection (3 papers, 2016 to 2025). "Similarly, orf virus infection of the human 3D skin model also induced a downregulation of KRT10 transcription, as well as KRT1 and loricrin, 8 or 10 days post-infection." (PMID 40694389, 2025).
acne (2 papers, 2014 to 2016). An inflammatory process of the sebaceous glands which is characterized by comedones, nodules, papules and/or pustules on the skin. "Overall, there are slightly less KRT1 peptides identified in acne samples (429 peptides) compared to nasal SFI samples (458 peptides), indicative of a slightly lower protein load in acne-A1 compared to nose-A1 samples." (PMID 25238151, 2014).
adenosquamous carcinoma (2 papers, 2004 to 2021). A carcinoma composed of malignant glandular cells and malignant squamous cells. "Since the pathological tumor tissue was adenosquamous carcinoma, we observed several keratins, including KRT1, KRT6B, KRTDAP, and KRT10, in C5." (PMID 34326696, 2021).
chronic periodontitis (2 papers, 2022 to 2025). A chronic inflammatory process that affects the tissues that surround and support the teeth. "Genes related to keratinocyte differentiation and the epidermal differentiation complex, including keratin family members (KRT1, KRT2, and KRT10) and loricrin (LOR), were also among the most downregulated genes in periodontitis." (PMID 41124422, 2025).
congenital ichthyosiform erythroderma (2 papers, 2019 to 2025). "Bullous congenital ichthyosiform erythroderma is a rare autosomal dominant condition characteristic caused by spontaneous mutations in the keratin 1 (KRT1) gene on chromosome 12 [12q13] and/or 17 [17q21-22]." (PMID 40291321, 2025).
coronary atherosclerosis (2 papers, 2020 to 2021). Atherosclerosis of the coronary vasculature. "Another example is that miR-107 activated the Notch pathway by targeting keratin 1 (KRT1) gene inhibition, consequently protecting VECs from inflammation and ER stress in a mouse model of coronary atherosclerosis." (PMID 32963706, 2020).
ichthyosis hystrix (2 papers, 2018 to 2022). "The result of this current work now demonstrates that ichthyosis hystrix of Curt Macklin is associated to both KRT1 and KRT10 mutations, when they lead to the disruption of the correct 2B-V2 hetero-domain, linking the disease to the loss of function of this structure." (PMID 29689068, 2018).
keratinization disorders (2 papers, 2014 to 2020). "Keratinopathic ichthyoses (KI) are a clinically heterogeneous group of keratinization disorders due to mutations in KRT1, KTR10, or KRT2 genes encoding keratins of suprabasal epidermis." (PMID 33081034, 2020). "Monoclonal antibodies to keratin 1 carboxy terminal (synthetic peptide) provide an important means of examining keratin expression in epidermal tumors and keratinizing disorders." (PMID 25050384, 2014).
keratinopathic ichthyosis (2 papers, 2016 to 2021). "We set out to investigate a rare form of keratinopathic ichthyosis caused by KRT1 mutation with two different optical imaging methods." (PMID 33562614, 2021).
lung carcinoma (2 papers, 2017 to 2022). "Hence, it can be assumed that the inhibited effect in cancer development induced by AFAP1-AS1 knockdown might be at least partly through the upregulated KRT1 in lung cancer." (PMID 29212176, 2017).
neuroblastoma (2 papers, 2021 to 2024). Neuroblastoma (NB) is the most common solid, extracranial childhood tumor. "It is noted that mouse as well as human KRT1 promoters were essentially inactive in both mouse and human neuroblastoma cells." (PMID 39066341, 2024). "Keratin 1 (K1) is a novel receptor, present on the surface of cancer cells (breast and neuroblastoma) and cells that have undergone oxidative stress, that is being used for targeted drug delivery." (PMID 34063098, 2021).
triple-negative breast carcinoma (2 papers, 2022). An invasive breast carcinoma which is negative for expression of estrogen receptor (ER), progesterone receptor (PR), and human epidermal growth factor receptor 2 (HER2). "The Kaur group is developing peptide-doxorubicin conjugates in order to treat triple-negative breast cancer (TNBC) by targeting cell-surface keratin-1 (K1) or epidermal growth factor receptor (EGFR) in cancer cells." (PMID 35631623, 2022). "Targeting KRT1 may represent a new method for treating triple-negative breast cancer." (PMID 36118853, 2022).
adenoma (1 paper, 2024). A neoplasm arising from the epithelium. "In addition to our proposed markers, KRT1, KRT2, and KRT10 were enriched in the C group among the stromal CDX2- population in our previous DVP experiment, consistent with the intensity increase observed in our larger adenoma cohort." (PMID 39252972, 2024).
Atrophy (1 paper, 2024). Any weakening or degeneration, especially through lack of use. "Notably, two atrophy-linked switch-like genes in the vagina that we identified, KRTDAP and KRT1, are crucial for the differentiation of epithelial cells in the vagina 48,49." (PMID 39315271, 2024).
autoimmune disease (1 paper, 2017). A disorder resulting from loss of function or tissue destruction of an organ or multiple organs, arising from humoral or cellular immune responses of the individual to their own tissue constituents. "In our previously study, we had detected the antibodies against KRT1 among patients with autoimmune diseases using the antigens encoded by three common KRT1 alleles mentioned in this paper." (PMID 29028840, 2017). "This study demonstrates that the variations in KRT1 and the specific polymorphism of KRT1 in this Chinese Han population are associated with autoimmune diseases SLE and SSc." (PMID 29028840, 2017). "Our data showed that the association between two KRT1 polymorphic sites and effects of autoimmune diseases SLE and SSc." (PMID 29028840, 2017). "Here, we present data to show the evidence of association between two major autoimmune diseases (SLE and SSc) and KRT1 genotypes." (PMID 29028840, 2017). "This information is very useful for us to explore that KRT1 gene variety involves in the pathogenesis of SLE, SSc and other autoimmune diseases." (PMID 29028840, 2017).
Autoimmunity (1 paper, 2023). The occurrence of an immune reaction against the organism's own cells or tissues. "Limited studies have highlighted the potential role of KRT1 in initiating and regulating autoimmunity." (PMID 38019813, 2023).
breast tumor (1 paper, 2024). "Furthermore, we assessed the expression of cytokeratins (CKs) commonly found in breast tumor cells (cytokeratin 1, 2, 3, 4, 5, 6, 7, 8, 10, 14, 15, 16, and 19)." (PMID 39456890, 2024).
cerebral cavernous malformation (1 paper, 2024). A disorder characterized by malformations in the structure of the capillaries in the brain. "High expression of KRT1 (Keratin 1) was observed to be protective against oxidative stress in the context of cerebral cavernous malformations." (PMID 39456899, 2024).
cyst (1 paper, 2022). A sac-like closed membranous structure that may be empty or contain fluid or amorphous material. "In cKO mice, a premature induction of Krt1 expression was observed at P14, and it persisted throughout the cyst formation, whereas less pronounced effects on Krt10 expression were observed at P14 to P18." (PMID 35247391, 2022).
eczema (1 paper, 2020). "Conversely, KRT1-deficient mice show impaired skin barrier function and have a gene expression signature similar to that observed in skin of human eczema patients." (PMID 33384449, 2020).
epididymitis (1 paper, 2021). Inflammation of the epididymis. "We found that Ccnyl1 expression was elevated; however, Sept4 and Krt1 were reduced in sperm from cauda epididymitis, indicating that the expression of flagella-related proteins was disturbed in Cabs1 KO mice." (PMID 33440775, 2021).
Fibroadenoma (1 paper, 2020). A benign tumor of the breast characterized by the presence of stromal and epithelial elements. "Furthermore, the expression of seven step-changing proteins (KRT10, KRT1, KRT6E, PLIN1, HBA2, FHL1, and ME2) were decreased in fibroadenoma tissues compared to fibroadenoma adjacent and normal tissues." (PMID 33194682, 2020). "For fibroadenoma tissues, compared with both fibroadenoma-adjacent and normal tissues, there were six up-regulated (ANXA6, VCP, SERPINH1, galactosidase alpha, NNT, and MMP11) and 38 down-regulated (KRT10, KRT1, ALDH1A1, ECM1, and others) proteins in fibroadenoma." (PMID 33194682, 2020).
hamartoma (1 paper, 2023). A benign and excessive tumor-like growth of mature cells and normal tissues which grow in a disorganized pattern. "Hamartoma and neoplasm of the eye were associated with KRT1, VHL and SLC25A11." (PMID 37185447, 2023).
head and neck squamous cell carcinoma (1 paper, 2025). A squamous cell carcinoma that arises from any of the following anatomic sites: lip and oral cavity, nasal cavity, paranasal sinuses, pharynx, larynx, and salivary glands. "Additionally, in vitro studies were conducted to assess the effects of KRT1 knockdown on cell invasion, migration, epithelial–mesenchymal transition (EMT), and apoptosis in head and neck squamous cell carcinoma (HNSCC) cell lines." (PMID 41002590, 2025). "In vitro studies showed that KRT1 knockdown suppressed tumor cell invasion, cell migration, and expression of epithelial–mesenchymal transition (EMT)-related genes in human head and neck squamous cell carcinoma (HNSCC) cell lines." (PMID 41002590, 2025).
hyperthyroidism (1 paper, 2023). Overactivity of the thyroid gland resulting in overproduction of thyroid hormone and increased metabolic rate. "Finally, possible causes of elevated serum KRT1 in hyperthyroidism could mainly be derived from a skin origin; however, thyroid and peripheral blood white blood cells (PBMCs) could be other potential sources." (PMID 38019813, 2023). "It was previously documented that KRT1 is tightly regulated by TH in keratinocytes, and can participate in skin manifestations in hyperthyroidism and hypothyroidism." (PMID 38019813, 2023). "Therefore, it is possible that in hyperthyroidism, elevated TH promotes excessive KRT1 production in the skin, is subsequently released into the blood circulation, and ultimately leads to a rise in serum KRT1 levels." (PMID 38019813, 2023).
keratoacanthoma (1 paper, 2016). A dome-shaped, rapidly growing skin lesion composed of well differentiated squamous cells. "Histological analysis showed that only neoplastic lesions originating from epidermal squamous cells were encountered, namely the atypical keratoacanthomas, which were positive for keratin 1, while being negative for S100." (PMID 27999416, 2016).
keratosis (1 paper, 2023). A skin disorder consisting of hypertrophy of the stratum corneum of the skin. "Also, NEPPK is a rare disorder that results from a genetic mutation in the N-terminal of keratin 1, a region that binds to desmoplakin, and clinically presents with keratosis of the palms and soles." (PMID 38203406, 2023).
kidney transplant (1 paper, 2017). A surgical procedure in which one or both kidneys from a donor are implanted into a recipient. "KRT1-IgG positivity was, therefore, associated with a higher risk of kidney transplant rejection (29.9% (23/77) versus 16.9% (30/178), p = 0.0187)." (PMID 28265584, 2017).